CXCL8 (C-X-C motif chemokine ligand 8)
Diseases named in the same sentence as CXCL8 in open-access papers (continued):
Sharing a sentence is not in itself a finding about the gene and the disease.
tumor (continued). "hnRNPAB enhances CXCL8‐dependent neutrophil recruitment by prolonging the half‐life of MYC mRNA in metastatic tumor cells." (PMID 40027151, 2025). "The activation of the CXCL8/CXCR2 signaling pathway is believed to suppress anti-tumor immunity, promote tumor cell invasiveness, and facilitate immune evasion." (PMID 40573881, 2025). "CXCL8 is a pleiotropic signaling molecule known to mediate CAF promotion of angiogenesis, EMT, and the recruitment of myeloid-derived suppressor cells and tumor-associated neutrophils." (PMID 40099972, 2025). "In the TME, CD56brightCD16- NK cells, the primary NK subtype in TME, can release VEGF, placenta growth factor, and IL-8/CXCL8, promoting angiogenesis and potentially supporting tumor growth." (PMID 40260236, 2025). "Immune microenvironment analysis revealed that blocking the CXCL8/CXCR1/2 pathway reduced the infiltration of MDSCs and tumor-associated neutrophils while enhancing the infiltration and activity of CD8+ T cells." (PMID 40573881, 2025). "Neovascularization, a basis for promoting tumor growth and metastasis, is now seen as a critical function of CXCL8 in the tumor microenvironment (TME)." (PMID 40124384, 2025). "These neutrophils also produce VEGF and CXCL8, which promote angiogenesis and recruit additional pro-tumor immune cells, such as macrophages and Tregs, into the TME." (PMID 40486614, 2025). "The observed anti-invasive phenotype strongly suggests that miR-101-3p suppresses tumor progression through translational repression of FN-1, CXCL8, and/or other more dominant pro-metastatic factors." (PMID 41382114, 2025). "Memory B cells secrete CXCL8 to attract DCs to tumor metastasis sites, strengthening antigen presentation and thus promoting T cell-mediated tumor killing." (PMID 41285707, 2025). "Temozolomide (TMZ), a common alkylating agent used in adjuvant chemotherapy for HGG, has been shown to upregulate the CXCL8-dependent CXCL2/CXCR2 axis, promoting angiogenesis and the recruitment of tumor-associated macrophages." (PMID 41432874, 2025). "Subsequent immunohistochemical analyses demonstrated that CXCL8 was mainly produced by the tumor cells." (PMID 40895532, 2025). "It has been reported that CXCL8 (IL8) promotes tumor proliferation, migration, and invasion and is an important component of senescent secretory proteins." (PMID 40510161, 2025). "Therapeutic strategies that precisely target the CXCL8 receptor to reduce immunosuppression in the TME and restore anti-tumor immune responses are likely to be the focus of future CXCL8 research." (PMID 41376630, 2025). "CXCL8 also exhibits dual roles in immune regulation: While it enhances anti-tumor immune responses via CD4+ T cell activation, it can also promote immunosuppression by inducing PD-L1+ macrophages." (PMID 40299331, 2025). "Chemokines like CCL2 and CXCL8 attract various immune cells, including macrophages and neutrophils, to the tumor." (PMID 41180630, 2025). "Neutrophils contribute to immune evasion by suppressing T-cell-mediated anti-tumor responses through the secretion of inhibitory cytokines like IL-10 and chemokines such as C-X-C motif chemokine ligand 8 (CXCL8), thereby facilitating tumor immune escape." (PMID 40565133, 2025). "Basophils secrete CXCL8, the most abundant cytokine in tumor tissue, and have been shown to be critical for metastasis." (PMID 40131539, 2025). "CXCL8 (IL-8), a direct transcriptional target of KRAS, is strongly associated with tumor-associated inflammation and angiogenesis." (PMID 40303413, 2025). "The CXCL8/CXCR1/2 axis has been identified as a key signaling pathway driving neutrophil recruitment to the tumor site; once recruited, TANs are exposed to local cytokines, including TGF-β, that further reinforce their immunosuppressive characteristics." (PMID 40281554, 2025). "Our investigation into the secretome of gemcitabine-resistant PDAC cells revealed elevated CXCL8 levels, a chemokine known to support tumor growth and chemoresistance." (PMID 41444422, 2025).
tumor (continued). "In the context of cancer, CXCL8 is produced by various cell types within the tumor microenvironment (TME), including infiltrating immune cells, stromal cells, and tumor cells." (PMID 40006729, 2025). "Higher CXCL8 expression in CRC tissue have been linked to more advanced disease stages, larger tumor size, deeper tissue invasion, distant metastases, and faster cancer progression." (PMID 40943634, 2025). "Their involvement in tumor inflammation is primarily driven by key pathways such as the CXCL8/CXCR2 axis, NF-κB signaling, ROS production, and the formation of NETs." (PMID 40550048, 2025). "CXCL8 is upregulated in various cancers, where it can promote tumor growth, invasion, angiogenesis, metastasis, and drug resistance through autocrine or paracrine mechanisms." (PMID 39962077, 2025). "Through CXCL8 signaling and other mechanisms, METs influence tumor cells and their ability to metastasize by initiating EMT, degrading the extracellular matrix and adhering to endothelial cells during extravasation." (PMID 40663561, 2025). "In C3, there was a high enrichment of genes that drive tumor cell proliferation and migration, notably C-X-C Motif Chemokine Ligand 8 (CXCL8) and pleckstrin (PLEK)." (PMID 40725006, 2025). "Specifically, CXCL3 drives the transformation of CAFs into myofibroblastic CAFs, facilitating tumor metastasis, whereas CXCL8 promotes tumor cell proliferation, EMT, and an immunosuppressive tumor microenvironment." (PMID 40725006, 2025). "As CSCs acquire enhanced immune evasion capabilities through epigenetic editing, they secrete substantial amounts of factors such as GM-CSF, CXCL1, CXCL2, and CXCL8, which recruit MDSCs to the tumor core." (PMID 41368628, 2025). "CXCL8 secreted by cancer cells in tumor microenvironment contributes to cancer cell proliferation, EMT and inhibition of apoptosis both in an autocrine and paracrine manner." (PMID 38900374, 2025). "CXCL1, CXCL2 and CXCL8 proteins were almost completely removed from the tumours after AEFs treatment." (PMID 39161078, 2025). "CTSZ, IFI30, CXCL8).Tumor NK cells were enriched for the d2 and d3 dog NK subclusters, classified by signaling and regulation, respectively." (PMID 41208961, 2025). "The expression levels of MMP1, TFRC, and CXCL8 were significantly upregulated in the tumor group compared to the normal group (p < 0.05)." (PMID 40809844, 2025). "We observed expression of tertiary lymphoid structure (TLS)-associated gene signatures including CD79A, CXCL8, and IL7R (interleukin-7 receptor) which supports the presence of well-organized TLS within the tumor microenvironment." (PMID 40950184, 2025). "The ability of CLU from TAMs to respond to tumor-derived CXCL8 was assessed using RNA sequencing, siRNA silencing, immunofluorescence and CCK-8 assays." (PMID 39905539, 2025). "METs serve multiple purposes; in this case, acting as a scaffold for the cleavage of tumor-secreted CXCL8 into its active, pro-metastatic form." (PMID 40663561, 2025). "The plasma cells were found to be affected by CXCL8 secreted by the tumor cells, and the predicted target gene was CD24." (PMID 40510161, 2025). "Specifically, cytokines involved in tumor progression such as CXCL8, EBI3, and IL1RN were upregulated in the triculture samples compared to other conditions." (PMID 40056038, 2025). "Several CAF-derived chemokines such as CCL2, CCL26, IL6, CXCL1, and CXCL8 mediate tumor progression, angiogenesis, and drug resistance, suggesting that tumor–CAF crosstalk is a bidirectional, dynamic, and adaptive process." (PMID 40447617, 2025). "Tumor grade demonstrated the strongest prognostic weight (C-index: 0.785 training, 0.750 validation), followed by CXCL8 expression and metastasis status." (PMID 40406253, 2025). "Lactate can also enter ECs through the monocarboxylate transporter MCT-1, trigger the phosphorylation/degradation of IκBα, and then stimulate the autocrine NF-κB/IL-8 (CXCL8) pathway, which drives tumor angiogenesis." (PMID 40562870, 2025).
tumor (continued). "CXCL8 chemoattracts TANs and induces extrusion of NETs, which shield tumor cells that ultimately limit the anti-PD-1 immune response to cancer." (PMID 38900374, 2025). "The downregulation of the IL-8 cytokine coding gene (CXCL8) in samples exposed to r-μg was interpreted as an indication that tumor cells are driven towards a less aggressive growth behavior." (PMID 41516217, 2025). "Active necroptosis in metastatic tumor cells recruits macrophages and induces the formation of macrophage extracellular traps (METs), accelerating tumor adhesion to endothelial cells via the CXCL8–ICAM‐1 axis." (PMID 40027151, 2025). "One approach is to stop the chemokines such as CXCL1, CXCL2, and CXCL8 (IL-8) that draw neutrophils to the tumor site to prevent their recruitment and usual overexpression in the tumor microenvironment." (PMID 41267750, 2025). "Analysis of clinical samples revealed that in SMAD4-negative cancers, the number of neutrophils in the peritumor stroma was markedly higher than in SMAD4-positive cases, and the CXCL8 was strongly expressed by infiltrating neutrophils in the tumor." (PMID 40943634, 2025). "In this study, we demonstrate that glutamine starvation activates two parallel signaling pathways, leading to the gene expression and secretion of the pro-angiogenic and pro-inflammatory interleukin-8 (IL-8/CXCL8) in tumor cells." (PMID 40683891, 2025). "EFNA1, CXCL8, and PPP1R14A emerged as prognostic biomarkers for CESC, showing significant associations with survival, tumor stage, and immune infiltration." (PMID 40406253, 2025). "Similarly, CXCL8, a chemokine implicated in tumor-related inflammation and immune modulation, could provide a unique window into the tumor microenvironment’s role in metastasis, distinguishing it from biomarkers like HER2, which are more associated with cell signaling and proliferation." (PMID 40087784, 2025). "Our RT-qPCR results confirmed the upregulation of MMP1, TFRC, and CXCL8 in the tumor group, which was consistent with the findings of our previous analyses." (PMID 40809844, 2025). "Secretion of CXCL8 by tumor cells modulated the expression of plasma cell CD24, which ultimately attenuated the activation of B cells into plasma cells." (PMID 40510161, 2025). "CAAs and CAA-derived CXCL8 cytokine modulate tumor growth, EMT, metastasis, and tumor immunity suppression." (PMID 40141437, 2025). "This highlights the potential of incorporating CXCL8 into liquid biopsy strategies, such as using circulating cytokine levels to monitor tumor progression or immune modulation in a minimally invasive manner." (PMID 41432874, 2025). "Key cytokines of interest include IL-6, TNF-α, IL-1β (as prototypical pro-tumor inflammatory cytokines), as well as others such as IL-8 (CXCL8), IL-10, and IL-17, which together shape the tumor immune microenvironment." (PMID 41007766, 2025). "Various CXC chemokine receptors are upregulated in HCC tumor cells, with CXCL2 and CXCL8 released by tumor-associated monocytes and with CXCL12 released by cancer-associated fibroblasts (CAFs) and stromal cells." (PMID 40721870, 2025). "The bar graphs indicated that the expression profiles of ATF3, CXCL2, RRAD, AREG, and CXCL8 in the C0 subtype were expressed at greater levels than in the remaining tumor cell subtypes." (PMID 40936936, 2025). "The activation of NF-κB subsequently promotes CXCL8 and the transcription factor P65 transcription, facilitating the migration of radiation-induced CD56dim NK cells from tumor cells and inhibiting tumor growth." (PMID 39744438, 2025). "The CXCL1/8-CXCR1/2 axis mediates the progression of multiple tumors, and high levels of CXCL1 and CXCL8 in tumors have been shown to be correlated with tumor burden and poor prognosis." (PMID 40148310, 2025). "PET tracers labeled with CXCL8 or its receptor can image neutrophil infiltration in tumors, which is crucial for studying tumor inflammation and the immunosuppressive microenvironment." (PMID 39911388, 2025).
tumor (continued). "Our results revealed a predominantly pro-inflammatory tumor microenvironment, driven by cytokines such as CXCL8, IL-6, and TNF-α, which create a favorable niche for tumor growth." (PMID 40895532, 2025). "Lin’s team confirmed through in vivo and in vitro experiments that BMSC can be recruited to the OSCC region and interact with OSCC cells to drive tumor progression via the CXCL8/CXCR2 and TGF-β/Ras/Raf/Erk signaling axes." (PMID 41445742, 2025). "CXCL1, CXCL5 and CXCL8 can recruit neutrophils and MDSCs and contribute to immune suppression and can also promote tumor cell migration and invasion of some tumor types." (PMID 40176808, 2025). "Tumor-derived CXCL8 fosters M2 TAM polarization by activating the STAT3 signaling pathway and concurrently hurdles PD-1+ CD8+ T cell recruitment." (PMID 40607254, 2025). "It is now a consensus that tumor-associated neutrophils (TANs) or PMN-MDSCs have a significant impact on tumorigenesis and CXCL8 and CXCL1/2 are of the most outstanding chemokines promoting protumoral immune responses." (PMID 38786066, 2024). "We found that 6 of 7 canine OS cell lines spontaneously produced large amounts of CXCL8, greater than 1000 pg/mL produced in 24 hours by 50,000 tumor cells on average." (PMID 38554158, 2024). "IL‐8 (CXCL8) is a chemokine released by tumor, stromal, and myeloid cells to attract myeloid cells to the tumor tissue and is involved in angiogenesis, tumor progression, and reduced response to ICIs." (PMID 37681284, 2024). "CXCR2 is of particular interest because its primary ligand CXCL8 exerts strong pro-tumor effects through recruitment of myeloid derived suppressor cells (MDSCs), enhancement of angiogenesis and increased tumor metastases." (PMID 38554158, 2024). "In the core gene set of CD44_NEU, we found that for some genes, such as CXCL8 (IL-8), the main role is to stimulate the migration and invasion of tumor cells, which can help tumor cells escape." (PMID 39684426, 2024). "Compared to that in CM derived from tumour cells cultured alone, the amount of the active form of CXCL8 (monomer) involved in MLKL-driven necroptosis was much greater in CM derived from the co-culture experiments." (PMID 39025845, 2024). "IL-8, commonly referred to as CXCL8, can exert angiogenic effects, which are crucial for tumor sustenance by ensuring that sufficient oxygen and nutrients are available for growth, thereby potentially underpinning tumorigenesis and metastasis." (PMID 39483474, 2024). "CXCL8, a chemokine, plays a crucial role in cancer biology by regulating immune responses within the tumor microenvironment." (PMID 38791448, 2024). "Conversely, PGE2-exposed pDCs release CXCL8, a chemokine that promotes tumor cell proliferation, migration/invasion and stimulates angiogenesis." (PMID 38504978, 2024). "It was found that there are significant differences in the levels of CXCL8 and the degree of tumor invasion (T factor) among patients with OC and those with OSCC." (PMID 38673838, 2024). "In vivo, treatment with an anti-CXCL15 antibody (CXCL15, a homologue of human CXCL8) abolished the METs formation in primary C57BL/6 orthotopic tumours." (PMID 39025845, 2024). "CXCL8 is a PitNET-derived cytokine that plays an important role in the tumor microenvironment to regulate tumor proliferation, invasion, and migration in an autocrine or a paracrine manner." (PMID 39295931, 2024). "Upregulation of CXCL8 expression on cancer cells is common across malignancies and is correlated with tumor progression and an overall worse prognosis." (PMID 39409924, 2024). "The tumor-released EVs induce neutrophil migration toward the tumor microenvironment through the chemokine receptor CXCR2/CXCL8 (IL8) axis, activating the PI3K-AKT pathway in the neutrophils." (PMID 39698539, 2024). "CXCL1 and CXCL8 induced tumor cell binding to brain endothelial cells, and endothelial cell tube formation/proliferation." (PMID 38786066, 2024).
tumor (continued). "CXCL8-CXCR1/2 axis is related to neutrophils or MDSCs recruitment, and CXCL8 affects immune cell functions, impacting tumor development." (PMID 38388484, 2024). "In PTC tissues, tumor cells recruit neutrophils by releasing CXCL8/IL-8 and reduce apoptosis rate of neutrophils through secretion of granulocyte colony-stimulating factor (GM-CSF)." (PMID 39290709, 2024). "Conversely, CXCL8 has been shown to trigger pro-angiogenic and anti-apoptotic pathways when it is secreted by tumor cells." (PMID 38542078, 2024). "ASCL2 is the master regulator of intestinal stem cell fate, and CXCL8 is an inflammatory chemokine elevated in the CRC tumor microenvironment, playing a crucial role in promoting angiogenesis, invasion, and metastasis." (PMID 39456726, 2024). "BRAF mutations can lead to the secretion of various cytokines and chemokines (such as CCL2, CCL5, and CXCL8) by tumor cells, altering the surrounding tumor microenvironment." (PMID 39529955, 2024). "High levels of CXCL8 have been found to induce epithelial-mesenchymal transition and promote the proliferation, migration and invasion of tumor cells through the JAK/STAT1/HIF-1α/Snail pathway." (PMID 39488622, 2024). "In the tumor tissue stage, monocytes remain active in the TME, interacting with tumor cells and other immune cells, marked by elevated expression of CXCL8, NAMPT, AQP9, and BCL2A1." (PMID 38720887, 2024). "IL‐8 (CXCL8) is arguably the most described chemokine in the context of cancer immunotherapy and is implicated in the promotion of tumour progression through the recruitment of immunosuppressive and pro‐tumourigenic cell populations." (PMID 39162097, 2024). "Microbial reads are disproportionately abundant within myeloid cells that up-regulate proinflammatory cytokines like IL1Β and CXCL8, while infected tumor cells up-regulate antigen processing and presentation pathways." (PMID 38959321, 2024). "This suggests that EIF4G1 knockdown in the H1299 cell line affects the chemotaxis of macrophages towards tumor cells by regulating CXCL8." (PMID 38405671, 2024). "Although we predict that CBX2-mediated regulation of TAM differentiation and activity is highly complex, our findings suggest a unique CBX2/CXCL1 or CBX2/CXCL8 axis in tumor cells that aid in remodeling the HGSC TIME." (PMID 38984891, 2024). "The serum concentration of CXCL8 in OC patients has been identified as a potential candidate for a tumor marker in both the diagnosis and progression of this malignancy." (PMID 38673838, 2024). "Critically, treatment with IFN-γ suppressed tumor-derived CXCL8, reducing TAM trafficking and enhancing anti-PD1 efficacy." (PMID 38339310, 2024). "Our results showed a favorable association between tumor-infiltrating immune cells and FN1, CXCL8, IL1β, and ITIH4." (PMID 38637796, 2024). "Although human CXCL8 can act on the murine homologs of human CXCL8 receptors, the limitation of the species difference between tumor cells and neutrophils must be considered." (PMID 39269257, 2024). "Our pseudotime analysis suggests a developmental trajectory of neutrophils that progresses from the healthy subtype to the tumor-specific population and finally a metastasis-specific population; a lineage that is largely driven by IL1β/CXCL8/CXCR2 axis." (PMID 38358352, 2024). "Brain metastatic variant tumor cells expressed CXCL1 and CXCL8 in a c-Met signaling-dependent manner." (PMID 38786066, 2024). "CXCL8, also called interleukin-8 (IL-8), is a multifunctional chemokine, regulating tumor proliferation, invasion, and migration, often via autocrine or paracrine pathways." (PMID 38388484, 2024). "Blockade of CXCL8 also reduced tumor burden in an orthotopic BCa model by downregulating NF-κB and subsequently lowering MMP-2 and MMP-9 expressions." (PMID 39409924, 2024). "High expression of CXCL8 promotes tumor development, while inhibition of CXCL8 expression can effectively inhibit tumor progression." (PMID 39188951, 2024).